UBQLN4 (ubiquilin 4)
Diseases named in the same sentence as UBQLN4 in open-access papers (continued):
Sharing a sentence is not in itself a finding about the gene and the disease.
cancer (continued). "Several studies have been reported on Ubqln4; however, little is known about the function of Ubqln4 in cancer, especially in GC." (PMID 29899380, 2019). "Firstly, we conducted a pan-cancer analysis of UBQLN4 using the TCGA database." (PMID 38969831, 2024). "Patients with high UBQLN4 mRNA levels had significantly poor prognoses in 20 of 32 cancer types." (PMID 36291176, 2022). "Importantly, we demonstrated that UBQLN4 DNA amplification is a positively selected mechanism in cancer progression and this mechanism is observed frequently even in the early phases of cancer development." (PMID 36291176, 2022). "In addition, a T cell killing assay also showed that ABZ pretreatment-induced enhancement of T cell-mediated cancer cell death was rescued by overexpression of UBQLN4." (PMID 35577504, 2022). "UBQLN4 was detected as a common essential gene across various types of cancer cell lines." (PMID 36291176, 2022). "The studies also demonstrate the UBQLN4 has multiple functions in responding to DNA damages and regulating protein clearance to prevent proteotoxic cell stress an event that would be quite active in proliferating cancer cells." (PMID 36291176, 2022). "Moreover, the analysis of CRISPR screen datasets showed that UBQLN4 is essential in 81.1% of all cancer cells (860 out of 1060)." (PMID 36291176, 2022). "Thus, in silico analysis does not support the possibility that miRs or genome DNA methylation are significant regulators of UBQLN4 mRNA levels in a pan-cancer analysis." (PMID 36291176, 2022). "Only 194 functional SNVs of the UBQLN4 gene in 40,549 patients for 40 cancer types (0.48%) and 86 functional SNVs of UBQLN4 in 10,953 patients (0.79%) in 32 cancer types were detected using the Catalogue of Somatic Mutations In Cancer (COSMIC) and TCGA datasets, respectively." (PMID 36291176, 2022). "A high proportion of samples in various types of cancers had CNA for UBQLN4." (PMID 36291176, 2022). "In conclusion, UBQLN4 was a promising prognostic biomarker of immune-related therapy in pan-cancer." (PMID 34539785, 2021). "Moreover, the role of UBQLNs family in cancer-related pathways in pan-cancer was analyzed using GSCA database to differentiate the function between UBQLN4 and other members in UBQLNs family." (PMID 34539785, 2021). "UBQLN4 is a novel driver gene of genomic instability in cancer." (PMID 34840594, 2021). "In conclusion, our study estimated the role of UBQLN4 in pan-cancer for the first time." (PMID 34539785, 2021). "Furthermore, the immunohistochemistry analyses of UBQLN4 protein in HPA database confirmed the overexpression of UBQLN4 protein in these cancers." (PMID 34539785, 2021). "Moreover, the role of UBQLN4 in cancer-related pathways in pan-cancer was analyzed using GSCA database." (PMID 34539785, 2021). "The UBQLN4 CNV landscape in 33 cancer types was performed by GSCA database." (PMID 34539785, 2021). "The methylation landscape of UBQLN4 in pan-cancer was also analyzed." (PMID 34539785, 2021). "Furthermore, UBQLN4 was identified as a common essential gene, and the dependency scores were ranked in the top 10 percentile across all genes in at least 90% of the cell lines, suggesting a key role in cancer cell lines establishment and perpetual survival." (PMID 36291176, 2022). "Hence, we evaluated the survival rates across various cancer types according to UBQLN4 mRNA levels." (PMID 36291176, 2022). "Regrettably, the role of UBQLN4 in pan-cancer remains unknown." (PMID 34539785, 2021). "Ubiquilin-4 (UBQLN4), a member of the ubiquilin family, has received limited attention in cancer research to date." (PMID 38969831, 2024). "UBQLN4 protein levels positively correlated with the CNV and mRNA levels in the Cancer Cell Line Encyclopedia (CCLE) datasets." (PMID 36291176, 2022). "The coexpression analyses of UBQLN4 mRNA and immune checkpoints and MMR signatures in pan-cancer were performed based on TCGA database." (PMID 34539785, 2021).
cancer (continued). "Spearman correlation between UBQLN4 CNV and methylation and immune cells infiltrate in pan-cancer was performed using GSCA database." (PMID 34539785, 2021). "However, the biological function of Ubqln4 remains largely unknown, especially in cancer." (PMID 29899380, 2019). "Our group has shown that UBQLN4 determines the balance of DDR pathways through the degradation of MRE11A which leads to resistance to DNA damaging agents and sensitivity to poly (ADP-ribose) polymerase inhibitor (PARPi), such as Olaparib in specific cancers." (PMID 36291176, 2022). "The Genomics of Drug Sensitivity in Cancer 2 (GDSC2) datasets also showed a negative correlation between UBQLN4 mRNA levels and Olaparib AUC values (Pearson correlation coefficient = −0.5, p = 0.011)." (PMID 36291176, 2022). "Of note, patients diagnosed with ACC, KIRC, MESO, SKCM, and UCEC cancer types and advanced—American Joint Committee on Cancer (AJCC) stage III and IV tumors who had high UBQLN4 mRNA levels showed a worse prognosis than patients with low UBQLN4 mRNA levels." (PMID 36291176, 2022). "Notably, higher expression of UBQLN4 predicted better OS, DSS, and PFI in GBM and LGG, indicating the heterology among various cancers." (PMID 34539785, 2021). "Further analysis provides a rationale for this finding by showing that UBQLN4 overexpression protects cells from acute genotoxic stress through enhancing the NHEJ-mediated sealing of DSBs, as NHEJ-driven mutagenesis is likely to be selected in cancer cells due to its error-prone mechanism." (PMID 34440334, 2021). "The rest four genes (YWHAG, ATXN1, UBQLN4, and SMAD9) also ranked high because of its high degree in transition probability W. Although they are not presented in CGC, some evidences show that these four candidate genes have functional roles in cancer or cancer-related biological processes." (PMID 31888623, 2019). "However, whether UBQLN4 is a valuable biomarker for the prognosis of immunotherapy in pan-cancer was not identified." (PMID 34539785, 2021). "Although ATXN1, SMAD9, UBQLN4 and GRB2 are not included in CGC, we have already mentioned that ATXN1, SMAD9 and UBQLN4 are all relate to cancers or pathway in the last paragraph." (PMID 31888623, 2019).
neurodegenerative disease (3 papers, 2014 to 2021). A disorder of the central nervous system characterized by gradual and progressive loss of neural tissue and neurologic function. "Of the mammalian ubiquilins, UBQLN1, UBQLN2 and UBQLN4 are expressed in the brain and are associated to varying degrees with neurodegenerative diseases characterized by protein misfolding, aggregation and mislocalization." (PMID 33431932, 2021).
UBQLN4 also shares sentences with these, for which no sentence is quoted: breast carcinoma (2 papers); depression (2); liver cancer (2); pancreatic adenocarcinoma (2); sarcoma (2); adenocarcinoma (1); adenocarcinoma of the stomach (1); Adrenocortical Carcinoma (1); Arrhythmia (1); atrial fibrillation (1); bladder cancer (1); cervical cancer (1); dissection (1); frontotemporal dementia (1); glioblastoma multiforme (1); head and neck squamous cell carcinoma (1); Huntington disease (1); leukemia (1); malignant mesothelioma (1); mucinous carcinoma (1); multiple myeloma (1); myeloma (1); osteosarcoma (1); Pan (1); paraganglioma (1); Parkinson disease (1); pheochromocytoma and (1); Pheochromocytoma and Paraganglioma (1); skin cutaneous melanoma (1); spinal muscular atrophy (1).
A further 1 disease shares a sentence with UBQLN4 in 1 paper.